RNU6-226P (RNA, U6 small nuclear 226, pseudogene)
Gene: Small nuclear RNA gene on chromosome 5 (175,703,898 to 175,704,004, forward strand). Ensembl gene ENSG00000200648.
Homologues: Orthologues: chimpanzee U6 (100% identical), macaque U6 (95% identical), guinea pig U6 (79% identical), pig U6 (75% identical). Paralogues in human: RNU6-509P (84% identical), RNU6-854P (84% identical), RNU6-1131P (83% identical), RNU6-166P (83% identical), RNU6-41P (83% identical), RNU6-621P (83% identical), RNU6-820P (83% identical), RNU6-1060P (82% identical), RNU6-11P (82% identical), RNU6-1274P (82% identical), RNU6-15P (82% identical), RNU6-242P (82% identical), and 1288 more.